PRKAA2 (protein kinase AMP-activated catalytic subunit alpha 2)
Diseases named in the same sentence as PRKAA2 in open-access papers (continued):
Sharing a sentence is not in itself a finding about the gene and the disease.
cancer (42 papers, 2012 to 2026). A tumor composed of atypical neoplastic, often pleomorphic cells that invade other tissues. "Variations in PRKAA2 expression are associated with the onset, development, and prognosis of several cancers, such as breast, ovarian, gastric, kidney, and liver hepatocellular carcinoma." (PMID 39001398, 2024). "PRKAA2 encodes the AMPKα protein, which functions as a metabolic sensor in many diseases, including cancer." (PMID 35626705, 2022). "Recent analyses of this database revealed that, while the PRKAA2 gene encoding AMPK-α2 is often mutated in human cancers, the PRKAA1 gene encoding AMPK-α1 (also, interestingly, the PRKAB2 gene encoding AMPK-β2) is often amplified instead." (PMID 33375416, 2020). "PRKAA2, which is the gene that encodes AMPKα2, has been shown to modulate cell proliferation and signalling pathways in different cancers, including bladder, pancreas and CRC." (PMID 32878019, 2020). "Recent studies have highlighted the significance of PRKAA1 and PRKAA2 in tumorigenesis and cancer progression." (PMID 39001398, 2024). "CDKN2A displayed higher mutation rates across multiple cancer types (31%), and other frequently mutated genes included LRPPRC (13%), PRKAA2 (11%), VLDLR (9%), ASNS (8%), GZMA (7%), GLS (7%), TNFRSF1A (6%), PSAT1 (5%), and PRDX6 (4%)." (PMID 37534256, 2023). "PRKAA2 is predominantly expressed in epithelial cells, particularly cancer epithelial cells." (PMID 39512680, 2024). "By contrast, the frequency of alterations in the PRKAA2 gene (encoding α2) in cancer is lower overall (note the different scales), and there is no obvious bias towards gene amplification or increased mRNA expression." (PMID 26934201, 2016). "We found that most of the mTOR pathway-related genes had a high expression level in most cancers, except for a few genes such as CAB39L and PRKAA2, which had a lower expression in most cancers compared to normal tissues." (PMID 34194607, 2021). "This regulation suggests a relationship between Cry1/2 and Bmal1 and Prkaa2, Ccnd1and Nf1 in promoting CJL mediated cancer." (PMID 31523185, 2019). "Others have cancer-relevant functions, such as steroid hormone synthesis (HSD17B8, earlier), and covalent modification of histones (HUWE1, IPO7, MLL4, PAXIP1, PRKAA2, all later except PAXIP1)." (PMID 23762276, 2013). "No significant equivalent sensitivity was noted for other cancer metabolic drugs such as PIK3CA (GDC0941 and AZD6482), GSK3A/B (SB 216763) inhibitors and PRKAA2 (AICAR and metformin) agonists." (PMID 24699711, 2014).
infection (6 papers, 2011 to 2024). The state of being infected such as from the introduction of a foreign agent such as serum, vaccine, antigenic substance or organism. "The expression of Prkaa2 increased following H37Rv infection, indicating its close association with the response to M. tuberculosis infection and implicating AMPKα2 in mediating the functions of ZNFX1." (PMID 38016036, 2024). "On the contrary, acting as the negative regulators, PRKAA2 and PRKACA, encoding the subunit of AMP-activated protein kinase (AMPK), which have been proven to inhibit glycolysis via AMPK-mTOR-HIF-1α pathway, were downregulated post infection." (PMID 37256871, 2023). "qPCR and Western blot analysis validated that the absence of ZNFX1 led to a significant downregulation of Prkaa2, irrespective of H37Rv infection." (PMID 38016036, 2024).
neurological disease (1 paper, 2012). "The significantly-populated signaling pathway “neurological disease” comprised both protein kinase, AMP-activated, alpha 2 catalytic subunit (Prkaa2) and ATP-binding cassette, subfamily D, member 2 (Abcd2)." (PMID 22934110, 2012).
PRKAA2 also shares sentences with these, for which no sentence is quoted: heart failure (20 papers); cardiac hypertrophy (16); hepatocellular carcinoma (7); lung carcinoma (7); endothelial dysfunction (4); Glucose intolerance (4); Hyperglycemia (4); myocardial ischemia (4); sarcopenia (4); skin cancer (4); diabetic cardiomyopathy (3); head and neck squamous cell carcinoma (3); hypertrophy (3); pulmonary hypertension (3); renal fibrosis (3); Arthritis (2); cardiomyopathy (2); Depression (2); endometrial cancer (2); glioblastoma (2); hypertrophic cardiomyopathy (2); iron deficiency (2); metabolic disease (2); metabolic dysfunction-associated steatotic liver disease (2); metabolic syndrome (2); osteoarthritis (2); ovarian carcinoma (2); steatosis (2); Stroke (2); Ureteral obstruction (2).
A further 56 diseases each share a sentence with PRKAA2 in 1 paper.